PTX3 (pentraxin 3)
Description:
Plays a role in the regulation of innate resistance to pathogens, inflammatory reactions, possibly clearance of self-components and female fertility.
Synonyms: TSG-14; TNFAIP5
Tractability: Antibody: its Gene Ontology location is reachable by antibodies, with high confidence; UniProt places it where antibodies can reach, with medium confidence; UniProt predicts a signal peptide or a membrane-spanning region.
Gene: Protein-coding gene on chromosome 3 (157,436,850 to 157,443,633, forward strand). Ensembl gene ENSG00000163661.
Subcellular location: Secreted
Subcellular location (Human Protein Atlas): Plasma membrane; Predicted to be secreted
Pathways (Reactome):
Immune System: Neutrophil degranulation
Gene Ontology:
Molecular function: complement component C1q complex binding; identical protein binding; protein binding; virion binding; (1->3)-beta-D-glucan binding
Biological process: host-mediated suppression of symbiont invasion; innate immune response; negative regulation by host of viral glycoprotein metabolic process; negative regulation of glycoprotein metabolic process; host-mediated suppression of viral proces; inflammatory response; immune response; immune system process; response to other organism
Cellular component: extracellular region; specific granule lumen; tertiary granule lumen; extracellular matrix
Genetic constraint (gnomAD): Loss-of-function variants: 28 observed, 29.02 expected, observed/expected ratio (o/e) 0.96, 90% interval 0.71 to 1.32. The upper end of that interval is the gene's LOEUF score, 1.32, which puts it in group 5 of 6, group 1 being the genes least tolerant of losing a copy. Missense variants: 510 observed, 463.03 expected, observed/expected ratio (o/e) 1.1, 90% interval 1.02 to 1.18. Synonymous variants: 218 observed, 188.12 expected, observed/expected ratio (o/e) 1.16, 90% interval 1.04 to 1.3.
Homologues: Orthologues: chimpanzee PTX3 (98% identical), macaque PTX3 (95% identical), pig PTX3 (84% identical), guinea pig PTX3 (83% identical), mouse Ptx3 (82% identical), rat Ptx3 (78% identical), rabbit PTX3 (76% identical), dog PTX3 (66% identical), tropical clawed frog ptx3 (48% identical), zebrafish ptx3a (39% identical), zebrafish ptx3b (37% identical). Paralogues in human: NPTX2 (22% identical), PTX4 (22% identical), NPTX1 (20% identical), CRP (15% identical), APCS (14% identical).
Diseases named in the same sentence as PTX3 in open-access papers:
PTX3 is named in the same sentence as 496 diseases in open-access papers, as found by Europe PMC text mining. Sharing a sentence is not in itself a finding about the gene and the disease. The quoted sentences say what the papers report.
Sepsis (98 papers, 2008 to 2025). Sepsis is defined as life-threatening organ dysfunction caused by a dysregulated host response to infection. "Our results confirmed that elevated serum PTX3 levels were significantly associated with sepsis or severe sepsis/septic shock and with bacterial infection." (PMID 40722110, 2025). "Abnormally elevated plasma PTX-3 levels are closely related to the mortality rate of sepsis and have important significance in predicting the risk of death for sepsis patients." (PMID 39021820, 2024). "Based on the definition of Sepsis-3, a combined biomarker approach that includes PCT, IL-6, pentraxin-3 and lactate showed promising results in predicting 28-day all-cause mortality in patients diagnosed with sepsis or septic shock." (PMID 38716051, 2024). "An essential part of innate immunity linked to sepsis is pentraxin 3, the first member of the long pentraxin subfamily to be discovered." (PMID 39294659, 2024). "A systematic review and meta-analysis of 16 studies involving 3,001 patients demonstrated that elevated PTX-3 levels significantly correlated with the increased severity of sepsis and higher all-cause mortality." (PMID 39201697, 2024). "PTX3 significantly improved cardiac function and structure in sepsis-stricken mice, and PTX3 alleviated cardiac damage caused by sepsis." (PMID 38784395, 2024). "The progress in understanding the role of PTX-3 in sepsis paves the way for improving diagnostic accuracy, prognostic assessment, and targeted therapeutic interventions." (PMID 39021820, 2024). "Elevated PTX-3 levels in blood samples have consistently been associated with more severe cases of sepsis and unfavorable outcomes." (PMID 39201697, 2024). "At the same time, by establishing a Cox proportional hazards model, it was found that the plasma PTX-3 level measured at admission is an independent predictor of the 28-day all-cause mortality rate of severe sepsis patients (HR = 7.16, 95% CI 2.46 ~ 15.85)." (PMID 39021820, 2024). "Higher levels of PTX3 were significantly associated with mortality, and PTX3 was a promising biomarker for the prognosis of sepsis." (PMID 35676730, 2022). "Platelet count was also found to be substantially lower in newborns with sepsis, and PTX3 was found to be adversely linked with platelet count in studies." (PMID 35449688, 2022). "A crunch of studies, none to the best of our knowledge, in the Indian subcontinent further emphasizes the need to assess the diagnostic utility of PTX3 in patients with sepsis." (PMID 36168379, 2022). "Increased levels of PTX3 have been associated with infectious disorders, including sepsis and septic shock, tuberculosis, dengue and meningitis." (PMID 36189302, 2022). "The pooled analysis suggested that high levels of PTX3 were significantly associated with mortality in patients with sepsis." (PMID 35676730, 2022). "IαI attenuates lung injury in a porcine model of lipopolysaccharide (LPS)-induced sepsis, and PTX3 deficiency worsens LPS-induced lung injury." (PMID 35634317, 2022). "Fewer studies investigated the distribution of PTX3 and its diagnostic and prognostic value among patients with sepsis or other critical illness." (PMID 34679604, 2021). "Since PTX3 seemed to be associated with the severity of sepsis, Spearman bivariate correlation analysis was evaluated between PTX3 and the following clinical indicators that reflected organ failures and disease severity." (PMID 34679604, 2021). "This study was carried out to investigate the diagnostic and prognostic value of PTX3 in patients with sepsis and septic shock based on Sepsis 3.0 definitions." (PMID 34679604, 2021). "The remaining six studies included in this review analyzed the presence of molecules potentially associated with neutrophil dysfunction in sepsis, such as pentraxin 3 (PTX3), ROS, and myeloperoxidase." (PMID 33111742, 2020).
Sepsis (continued). "Similar increases in plasmatic levels of PTX3 and associations with mortality in patients with sepsis or septic shock were reported in other studies." (PMID 31057548, 2019). "The diagnostic and prognostic value of circulating PTX3 was tested in recent studies on patients with severe sepsis and septic shock." (PMID 31057548, 2019). "The present study evaluated the diagnostic values of MCP1, PTX3, Ang1 and Ang2 in patients with sepsis and septic shock according to the latest Sepsis 3.0 definitions." (PMID 31489646, 2019). "In sepsis, PTX3 plasma levels are associated with severity of the condition, patient survival, and response to therapy." (PMID 31031772, 2019). "IL-6 and PTX3 can be used as both diagnostic and prognostic biomarkers for sepsis and septic shock diagnosed in accordance with the Sepsis-3 definitions." (PMID 31718563, 2019). "In patients with necrotizing soft tissue infections, PTX3 plasma levels were associated with amputation and were higher in individuals with sepsis." (PMID 31031772, 2019). "Evidence concerning the clinical value of IL-6 and PTX3 is controversial; however, prior studies have proposed PTX3 as a diagnostic and prognostic marker of sepsis." (PMID 31718563, 2019). "The present study evaluates the diagnostic value of PTX-3 in patients with sepsis and septic shock according to the latest Sepsis-3 definitions during the first week of intensive care treatment." (PMID 28793880, 2017). "PTX3 association with sepsis was proven, and the effect of antioxidant treatment on PTX3 levels was demonstrated." (PMID 27403446, 2016). "Higher levels of PTX3 were associated with the development of sepsis, severe sepsis, and septic shock." (PMID 25530683, 2014). "In patients with suspected infection, a high PTX3 level (≥14.1 ng/mL; optimal cut-off value for severe sepsis) was associated with several endpoints reflecting the severity of the disease (need for ICU stay, hypotension, and acute renal insufficiency)." (PMID 25530683, 2014). "Early elevated PTX3 levels are associated with more severe forms of sepsis, number of organ failures and poor outcome." (PMID 23341967, 2013). "A high PTX3 level (≥14.1 ng/ml; optimal cut-off value for severe sepsis) was associated with day 28 case fatality and several endpoints reflecting the severity of the disease (need for ICU stay, hypotension and acute renal insufficiency (p<0.001))." (PMID 23341967, 2013). "Higher levels of PTX3 were associated with the development of sepsis, severe sepsis and septic shock (p = 0.0001)." (PMID 24039869, 2013). "The PTX3 complex has the potential to be a highly useful diagnostic marker of sepsis and other inflammatory diseases." (PMID 23248627, 2012). "Sprong and associates have shown that PTX3 levels correlate significantly negatively with fibrinogen levels in sepsis." (PMID 21423699, 2011). "In accord with the present findings, a high PTX3 level has previously been shown to be associated with mortality in severe sepsis and septic shock and to be an early indicator of shock in severe meningococcal disease." (PMID 21423699, 2011). "In recently published studies, a high PTX3 level has been shown to be associated with mortality in severe sepsis and septic shock, and to be an early indicator of shock in severe meningococcal disease." (PMID 21423699, 2011). "Elevated PTX3 levels in plasma have been linked to infection severity, particularly in sepsis." (PMID 39762781, 2025). "In contrast, according to the current qSOFA classification, used in Sepsis‐3 definition proposed in 2016, CLU levels decreased more in patients with qSOFA ≥2, indicating a high risk of sepsis‐related mortality, while PTX3 seemed less marked with this classification." (PMID 40722110, 2025). "PTX3 was shown to improve cardiac impairment caused by sepsis in mice." (PMID 38784395, 2024).
Sepsis (continued). "Thus, elevated early PTX-3 levels were indicative of subsequent organ failures, and a less significant decrease in PTX-3 levels over time was linked to increased mortality risk in severe sepsis and septic shock." (PMID 39201697, 2024). "Human chorionic gonadotropin, a hormone first identified in the placenta, can reduce the expression of pro-inflammatory mediators (TNF-α, IL-6, and Pentraxin 3) and chemokines (macrophage inflammatory protein 1-a and chemotokine ligand 5) caused by sepsis, and improve organ damage caused by sepsis." (PMID 37629199, 2023). "Hence, the novel marker PTX3 with its advantages needs to be considered and to be studied in future studies, as sepsis is one of the most common causes of mortality in humankind, which should be emphasized." (PMID 36168379, 2022). "Numerous studies done to date have noticed that PTX3 has an excellent diagnostic value in sepsis." (PMID 36168379, 2022). "PTX3 has also been studied as a diagnostic biomarker for sepsis." (PMID 33912155, 2021). "Multivariate analysis revealed that PTX3 alone was a better risk factor for mortality, whether in sepsis and septic shock patients." (PMID 34679604, 2021). "•Multimer formation of pentraxin-3 (PTX3) has been linked to outcome in sepsis." (PMID 33288685, 2021). "While there is a general consensus on the increase of PTX3 plasma levels in septic patients, and the correlation with severity from SIRS to sepsis and septic shock, the diagnostic superiority of PTX3 over other biomarkers, such as PCT, IL-6, CRP and lactate, is still under debate." (PMID 31031772, 2019). "PTX3 was proposed as a diagnostic and prognostic marker for sepsis." (PMID 31718563, 2019). "Similarly, PTX3 in combination with IL-6 improved the risk stratification of patients with sepsis or septic shock as classified using the updated sepsis-3 definition." (PMID 31031772, 2019). "PTX3 can be measured in plasma in nanogram amounts in patients with sepsis and shock and if measured serially, may have utility in risk assessment in sepsis and shock." (PMID 30227609, 2018). "Novel biomarkers such as PTX-3 in combination with established ones such as IL-6 might improve the individual time-dependent risk-stratification of patients with sepsis or septic shock." (PMID 28793880, 2017). "Therefore, this study applies these definitions and aims to investigate the diagnostic value of PTX-3 in patients with sepsis and septic shock during the first week of intensive care treatment." (PMID 28793880, 2017). "PTX-3 reveals diagnostic value for sepsis and septic shock during the first week of intensive care treatment, comparable to interleukin-6 according to latest Sepsis-3 definitions." (PMID 28793880, 2017). "The diagnostic value of PTX3 is low in patients with sepsis." (PMID 25530683, 2014). "High PTX3 has been shown to be associated with mortality in severe sepsis and bacteremic patients." (PMID 23341967, 2013). "PTX3 encodes for an acute phase protein produced by monocytes, macrophages and endothelial cells and, as reported by several reports, its expression is high in plasma of patients with sepsis, acute myocardial infarction and severe atherosclerosis." (PMID 23663527, 2013). "In addition to its anti-pathogenic activity, PTX3 also has been shown to play a role in protecting against severe inflammatory reactions in animal models of sepsis, seizure-induced neurodegeneration and acute myocardial infarction." (PMID 23248627, 2012). "Therefore, PTX3 level was linked with both disease severity and mortality in sepsis." (PMID 35676730, 2022). "Of note, PTX3 has been described as associated with IL-10 in atherosclerosis experimental conditions and could help to counteract the pro-inflammatory response observed in sepsis." (PMID 30687307, 2018). "Recent studies indicate that high levels of PTX3 may be associated with mortality in sepsis." (PMID 21423699, 2011).
Sepsis (continued). "The prognostic value of PTX3 has been assessed across various diseases, including COVID-19, lung cancer, vasculitis, and sepsis (11, 12, 17, –, 19)." (PMID 39878524, 2025). "Pentraxin 3 (PTX3) acts as a serum acute-phase protein, upregulated rapidly during sepsis, endotoxic shock, and infectious conditions." (PMID 40428786, 2025). "PTX3 and pro‐inflammatory cytokine levels increased according to sepsis severity in patients with FN." (PMID 40722110, 2025). "Hamed and colleagues, for example, investigated the usefulness of PTX3 in septic patients and found that it was as useful as IL-6 in diagnosing sepsis and septic shock in the first week of intensive care therapy." (PMID 40426899, 2025). "Their findings suggest that PTX3 regulates TLRs signaling and protects against sepsis-induced intestinal mucosal damage." (PMID 40386784, 2025). "Short pentraxin CRP and long pentraxin PTX3 are not only sepsis biomarkers but have also been shown to induce the upregulation of cell adhesion molecules on immune cells and trigger complement activation." (PMID 39951217, 2025). "Similarly, PTX3, an acute-phase inflammatory mediator produced and released at the infection site, is also linked to Aspergillus, but it lacks good specificity, associated with a variety of infections and inflammatory diseases, such as bacterial pneumonia and sepsis (32, –, 34)." (PMID 40401965, 2025). "The role of PTX3 is well established in sepsis due to bacteria, with a predictive value for severe sepsis and mortality consistently demonstrated, along with a strong correlation between PTX3 levels and SOFA score." (PMID 40722110, 2025). "Among the most promising biomarkers, pentraxin-3 (PTX-3) has emerged as a critical indicator of sepsis severity." (PMID 40265185, 2025). "In this review, we provide an overview discussing the latest advancements in the study of PTX-3 as a biomarker for sepsis." (PMID 39021820, 2024). "Elevated PTX-3 levels have been observed in various infectious diseases including sepsis, septic shock, aspergillus infection, tuberculosis and dengue fever." (PMID 39021820, 2024). "In different studies, the optimal cut-off value of PTX-3 for predicting bacterial infection, sepsis, septic shock and mortality varies, and the reported sensitivity and specificity are also discrepant." (PMID 39021820, 2024). "This indicated that PTX3 decreased the apoptotic capacity of cardiomyocytes in mice myocardial injury induced by sepsis." (PMID 38784395, 2024). "The findings of our study are derived primarily from endotoxemia models established in mice, indicating PTX3 can be used as a potential predictive and therapeutic targe for sepsis." (PMID 39666228, 2024). "In a multicenter trial, the clinical and prognostic value of PTX-3 was investigated in a cohort of 958 patients diagnosed with severe sepsis or septic shock." (PMID 39201697, 2024). "Some studies have highlighted the added value of PTX-3 in combination with other biomarkers like procalcitonin in improving the accuracy of sepsis diagnosis and prognosis." (PMID 39201697, 2024). "In conclusion, PTX3 inhibits apoptosis caused by excessive autophagy by inhibiting the PI3K/AKT/mTOR signaling pathway, thereby alleviating the progression of sepsis." (PMID 38784395, 2024). "This study has corroborated that PTX3 mitigates sepsis-provoked myocardial injury in mice through lentiviral-mediated overexpression and counteracts myocardial injury in LPS-induced septic mice." (PMID 38784395, 2024). "The cut-off values of PTX-3 and other commonly used indicators in differencing infection, sepsis and predicting mortality." (PMID 39021820, 2024). "As an acute-phase reactant protein, PTX-3 has been widely studied as a biomarker to distinguish common bacterial infections from sepsis or septic shock." (PMID 39021820, 2024). "The findings contribute significantly to our understanding of the role of PTX3 in liver injury and innate immunity, potentially opening new avenues for sepsis treatment." (PMID 39666228, 2024).